ENSG00000259371 (novel protein)
Gene: Protein-coding gene on chromosome 14 (24,120,956 to 24,131,829, forward strand). Ensembl gene ENSG00000259371.
Genetic constraint (gnomAD): Loss-of-function variants: 11 observed, 21.93 expected, observed/expected ratio (o/e) 0.5, 90% interval 0.31 to 0.83. Missense variants: 231 observed, 270.13 expected, observed/expected ratio (o/e) 0.86, 90% interval 0.77 to 0.95. Synonymous variants: 105 observed, 109.83 expected, observed/expected ratio (o/e) 0.96, 90% interval 0.81 to 1.12.